TNF (tumor necrosis factor)
Diseases named in the same sentence as TNF in open-access papers (continued):
Sharing a sentence is not in itself a finding about the gene and the disease.
infection (continued). "Consequently, the enhanced expression of CCL2/MCP1, PTX3 and TNFα observed after infection with D26 could indicate a heightened disease risk from an NF-kB-driven inflammatory response by an ORF6 deletion variant." (PMID 33399033, 2021). "Tumor necrosis factor α (TNFα) is a member of the proinflammatory cytokines and plays a key role in regulating immune cell activation/migration, cell proliferation/apoptosis, angiogenesis, and insulin resistance/growth impairment caused by chronic stress/infection." (PMID 32082258, 2020). "The increase of IFN-γ and TNF-α after the infection observed in the knockout mice might be associated with a greater defense of the intestine against the invasion of B. abortus, which might be contributing to the phenotype of resistance observed in these animals." (PMID 32353980, 2020). "Limited data suggest that patients on TNF-α inhibitors may be more susceptible to infection." (PMID 32185141, 2020). "The inability of a VL patient to mount protective Th1 immune response (IL-2 IFN-γ, TNF- α), exacerbates the pathogenicity and in some cases results in resistance to drug.There are reports that when over expression of IL-10, render the resistant mice, susceptible to infection." (PMID 32555598, 2020). "We subsequently studied differences in the host response between low and high TNF-α producers amongst CAP patients by using a targeted approach through measuring 15 plasma biomarkers providing insight in key host response pathways implicated in the pathogenesis of severe infections." (PMID 32477337, 2020). "Hence, TNF-α has been implicated in the initial events of the infection, in direct leishmanicidal activity and thus controlling the multiplication of the parasite, developing effective acquired immunity for long term control of the disease as well as mediating the disease expression." (PMID 31469834, 2019). "It is unclear how contacts who do not convert to TST positivity despite frequent exposure to M. tb prevent the establishment of infection, although studies of genetic susceptibility suggest that TNF-mediated effector mechanisms may influence innate resistance to M. tb infection." (PMID 31497538, 2019). "Immunosuppressive anti-TNFα therapy in humans is linked to a higher susceptibility for an infection with Leishmania or a reactivation of latent leishmaniasis, including reports that suggest differences in parasite control depending on the type of TNFα blocker applied." (PMID 30108591, 2018). "Although infections are typically attributable to neutropenia in MDS patients, those with IO may also have reductions in key immune cytokines (e.g., TNFα, IFNγ), impaired nitric oxide production, and loss of T-cell function, which can further contribute to infection risk." (PMID 30719392, 2018). "Therefore, it is necessary to perform Toxoplasma serological testing in patients before treatment with etanercept and other biological anti-TNF agents, in addition, patients who have been treated with these drugs should be recommended to avoid the risk of infection with T. gondii." (PMID 30519229, 2018). "Anti-TNF-α agents may cause injection site reactions and increase the risk of infection." (PMID 30373275, 2018). "In addition, the deficiency of IL-6, IL-23, or IL-17 receptor A (IL-17RA) impaired the compact granuloma formation and conferred susceptibility during infection, associated with reduced tumor necrosis factor-α, IFN-γ, and inducible nitric oxide synthase enzyme expression." (PMID 28871251, 2017). "(CSC, ESC) were evaluated to choose the promising antigen that could be used in early diagnosis of strongyle infection along with the immunoassay that incorporated the measuring of Th1 (TNF-α) and Th2 (IL-4) cytokines to be used as a diagnostic tool refers to the stage of infection." (PMID 28717322, 2017).
infection (continued). "Although the strength of association between anti-TNFs and the risk of infection remains a topic of debate, the evidence published so far underscores the need for clinicians to carefully balance the clinical benefits and potential harms of initiating anti-TNF therapy in individual patients." (PMID 29246162, 2017). "Therefore reduced secretion of TNF-α could be beneficial for the fetal environment, albeit bearing the risk of reduced capacity to fight of infection and of prolonged activation of immune effector cells by due to missing pro-apoptotic signaling." (PMID 28793310, 2017). "It is highly plausible that the diversion of the pro-inflammatory to anti-inflammatory response in carriers of the rs3750920 TT genotype may expose the individual to a higher risk as TNF and, IL-6 cytokines are important early in infection to keep the parasite in check." (PMID 28288644, 2017). "However, IL-6 and TNF-α expression in infected wild-type DCs decreased significantly with DenV2 infection, in comparison with infected TLR2-deficient DCs (227 ± 16 vs. 178 ± 11 for IL-6 MFI in BL/6 and TLR2 KO; 259 ± 9 vs. 218 ± 11 for TNF-α MFI in BL/6 and TLR2 KO)." (PMID 29285314, 2017). "During the infection process of invasive S. aureus, pathogen-associated-molecules initiate the innate immune system leading to activation and recruitment of neutrophils and macrophages and the production of pro-inflammatory cytokines, most notably TNF-α, IL-1β, and IL-6." (PMID 27917374, 2016). "While highly susceptible TNF-α deficient mice succumbed with overwhelming M. tuberculosis infection, and IL-1RI deficient mice showed intermediate susceptibility, IL-36R-deficient mice controlled the infection, with bacterial burden, lung inflammation and pathology, similar to wild-type controls." (PMID 25950182, 2015). "Indeed, the low influx of PMN cells to the site of infection and the decreased production of TNF-α and IL-12 associated with enhanced production of IL-10 detected 48 h after infection of MLT-treated B10.A mice indicated a prevalent LX signaling when CysLTR1 was blocked." (PMID 26635449, 2015). "Accordingly, serious fungal, mycobacterial, and bacterial infections have been reported to be associated with treatment with TNF-alpha antagonists; however, the different pharmacodynamic and pharmacokinetic properties of these agents might change their associated risks of infections." (PMID 25755904, 2015). "In obese mice, chronic inflammation caused by mediators such as TNF-α can cause skin gamma delta T cells to be unresponsive to damage in the epithelium, preventing the release of cytokines and growth factors that facilitate wound repair and making the wound vulnerable to injury and infection." (PMID 24701367, 2014). "A recent systematic review of over 23,000 patients using anti-TNF therapy in the treatment of RA, juvenile idiopathic arthritis, ankylosing spondylitis, psoriatic arthritis, psoriasis and Crohn's disease, has further characterized infections associated with biologics." (PMID 25414636, 2014). "Besides an extracellular or extrinsic role of enhancing antibodies, ADE may also enhance infection intrinsically by regulating the production of inflammatory-associated cytokines, such as IL-6, IL-10, IL-12, TNF-α and IFN-γ." (PMID 25329914, 2014). "The potential causal link between infection and preterm birth is consistent with models suggesting that preterm labor is triggered by an inflammatory response mediated by pro-inflammatory cytokines such as interleukin (IL)-1beta, IL-6, IL-8, and tumor necrosis factor (TNF)-alpha." (PMID 25105549, 2014). "However, presence of either IL-1α or IL-1β in single-deficient mice is sufficient to control acute M. tuberculosis infection, with restrained bacterial burden and lung pathology, in conditions where TNF deficient mice succumbed within 4 weeks with overwhelming infection." (PMID 25400917, 2013).
infection (continued). "Consequently, TNF-α-deficient mice remain more susceptible to infection with A. fumigatus." (PMID 23971044, 2013). "Therefore, DAAP may be used as a synergistic as well as an alternative treatment for RA patients who are responding poorly to a TNF-α blocking agent and for those patients at high risk of infection or malignancy." (PMID 23945080, 2013). "A possible association between oscillatory behavior of TNF-α and rhythmic neuronal NF-κB activity, which has been found to affect thermoregulation, could be related to changes in ultradian spectral fluctuations of temperature signals during infection." (PMID 22424316, 2012). "Therefore, the large number of recruited monocytes may compensate for the loss of TNFα expression caused by neutrophil depletion at the localized infection site." (PMID 22496642, 2012). "Although strong antibody responses are important for clearance of and protection against HBV infection, the Th1-cell and CTL response to HBV and the associated antiviral cytokines (IFN-γ, TNF-a, and IL-2) may play a key role in virus resolution during natural infection." (PMID 22970140, 2012). "However, it is also known that anti-TNF therapy may be a risk factor for a number of infections; in particular, IFX treatment is considered as a risk factor for reactivation of latent tuberculosis." (PMID 22405136, 2012). "Moreover, susceptible IL-4 KO mice treated with TNF-α are able to clear infection." (PMID 23053395, 2012). "Engagement of these receptor molecules during infection with S. pyogenes, a largely extracellular bacterium with limited capacity for intracellular survival, causes innate immune cells to produce inflammatory mediators such as TNF, but also type I interferon (IFN)." (PMID 21625574, 2011). "In contrast, infection with the non-invasive carriage isolates is associated with protection of epithelial cells mediated by the shedding of sTNFR1 resulting in alteration of the biological activity of TNF-α through soluble receptor-ligand complex formation and abrogation of apoptosis." (PMID 22144896, 2011). "Considering the important role of TNF-α in the maintenance of the balance host-parasite in the infections caused by these two microorganisms, its absence in the infections due to M. paratuberculosis could be related to the chronicity of the pathologies caused by this microorganism." (PMID 22151930, 2011). "In contrast, Tm-TNF showed an increase in body weight comparable to WT mice for the first 130 days post-infection but significant weight loss was recorded in Tm-TNF mice between 237 days and 265 days post-infection while the body weights in WT mice remained stable." (PMID 22132068, 2011). "Indeed, for filoviruses it has been shown that this infection triggers the secretion of high levels of pro-inflammatory cytokines, particularly TNF-α, which then cause changes in the permeability of the vascular endothelium that lead to the clinical manifestations of hemorrhage and shock." (PMID 21572983, 2011). "A low level of TNF α and its receptors may increase susceptibility to infections." (PMID 20640152, 2010). "Plasma TNF-alpha levels have been described as a biomarker for the estimation of disease severity for P. falciparum and is associated with clinical severity in P. vivax infections, but there is scarce data evaluating or validating more sensitive and reliable predictors of severe disease." (PMID 20386593, 2010). "Therefore, while UBD is expressed more highly in naïve susceptible animals, upon infection with nematodes the resistant animals may induce UBD expression to a higher level than the susceptible animals in a TNFα-dependent manner." (PMID 16515715, 2006). "Again, the role played by TNF-α in the activation of phagocytic cells and the involvement of these cells in the host defence against infections suggest that impairment in phagocytic cell activity may heighten the risk for infection during TNF-α neutralization." (PMID 15743471, 2005).
infection (continued). "The cytokine storm refers to the excessive activation of the immune system following infection, resulting in the massive release of various inflammatory cytokines, such as tumor necrosis factor‐alpha (TNF‐α), interleukin (IL)‐1β, and IL‐6." (PMID 41551210, 2026). "During the infection process, Candida albicans activate dendritic cells and macrophages, inducing the release of specific cytokines such as tumor necrosis factor α (TNF-α), IL-6, IL-10, and IL-18." (PMID 41607541, 2026). "As expected, infection with the P. aeruginosa PAKΔSTY mutant strain—which lacks T3SS effectors—strongly upregulated TNF-α expression at both the mRNA and protein levels in THP-1 monocytes." (PMID 41596763, 2026). "The abundance of Enterobacteriaceae or Escherichia-Shigella was positively correlated with rectal temperature at 12 and 24 h post-infection, serum TNF-α level, and jejunal IL-1β, IL-10, and TNF-α mRNA levels." (PMID 41547922, 2026). "During early kidney injury, M1 macrophages, induced by IFN‐γ and pro‐inflammatory signals, highly express iNOS and CD86, releasing IL‐1β, IL‐6, and TNF‐α to combat infection." (PMID 41527491, 2026). "In p62-deficient macrophages, we observed reduced expression and secretion of key cytokines, such as IL-1β, TNFα and IL-6, early during infection." (PMID 41583695, 2026). "While IL‐1β, TNF‐α, and IL‐6 exhibited a declining trend following the initial peak within 72 h, implying potential resolution of the initial infection, the trajectory of HMGB1 levels remained inconspicuous and even continued to rise in the spleen until 72 h." (PMID 41551210, 2026). "We found Aph infection induced the expression of the hepcidin mRNA and protein, and strong IL-6, IL-1β, and TNF-α mRNA expression by host cells." (PMID 42294677, 2026). "IFN-γ production is also influenced by TNF-α and is important for responses to a wide range of infections, inducing macrophage activation, and is produced by Th1 cells, among others." (PMID 41602558, 2026). "In controls and monkeys infected with the acute strain, TNF-α levels remained stable throughout the infection." (PMID 41602558, 2026). "IL-17 stimulates the production of other pro-inflammatory cytokines, such as IL-6, IL-1β, and TNF-α, and induces the production of chemokines that recruit neutrophils to the site of infection, amplifying the inflammatory response." (PMID 40145967, 2026). "Conversely, resistance to infection is associated with a Th1 profile, characterised by high production of IL‐12, interferon‐gamma (IFN‐γ) and tumour necrosis factor‐alpha (TNF‐α), and the presence of M1 macrophages with high NO production." (PMID 41500977, 2026). "TNF-α, one of the main pro-inflammatory cytokines, is an inducer of local inflammatory response during infection." (PMID 40360766, 2026). "This study aimed to describe the cytokine responses (IL-2, IL-6, IL-10, TNF-α, IFN-γ) associated with each infection." (PMID 41547724, 2026). "Analysis of inflammatory mediators revealed selective modulation of cytokine expression, with reduced interleukin-6 transcript levels at 20 days post-infection, whereas tumor necrosis factor alpha expression remained unchanged." (PMID 42081053, 2026). "Infection with MTB provokes immune cells to secrete inflammatory mediators such as Tumor Necrosis Factor‐alpha (TNF‐α) and interleukins (ILs)." (PMID 41477556, 2026). "Both RV‐16 and RV‐1A induced significant increase in production of IL‐17 and TNF‐α in TMNCs at 24 h post‐infection (hpi) compared to mock‐inoculated cultures." (PMID 41578919, 2026). "We show that certain orthologous genes and orthologous pathways are differentially regulated upon infection among the three species like pathways related to translation rRNA processing and TNF-alpha signalling." (PMID 41683687, 2026).
infection (continued). "Upon pathogen encounter, macrophages secrete cytokines such as IL-6, IL-8, TNF, and C-C motif chemokine ligands (CCLs) to recruit monocytes to sites of infection, an essential process for effective host defense and maintenance of immune homeostasis." (PMID 41576161, 2026). "Concurrently, infection triggered a pronounced pro-inflammatory response, with mRNA levels of IL-1β, IL-6, IL-8, and TNF-α significantly upregulated." (PMID 41584086, 2026). "Transcriptomic analysis results showed that NC infection activated the interleukin (IL)-17 and tumor necrosis factor (TNF) signaling pathways, increasing the expression of chemokines (CXCL1/2/3) and inflammatory genes (FOSB)." (PMID 41669237, 2026). "In response to infection, a strong interaction between the cytokines IL-12 and TNF-α was observed in the groups treated with quercetin." (PMID 41841172, 2026). "Collectively, these findings demonstrate that D. pinnata extract effectively suppresses infection-induced TNF-α expression across different cell types." (PMID 41596763, 2026). "TNF has a dual effect in Plasmodium infection, bolstering the host's immune defense while also inducing sickness behavior." (PMID 41648113, 2026). "CONCLUSION: The crude incidence rates of SAEs and serious infections among AMGEVITA® users were within the range observed for the anti-TNF comparator cohort." (PMID 42015260, 2026). "The systemic presence of PGE2 in CL, together with TNF‐α and IL‐12, induces immune system activation capable of controlling the infection." (PMID 41500977, 2026). "Post-infection depletion of neutrophils rescued mice from lethal infection by significantly reducing the bacterial burden and levels of IL-17A, IL-6, and TNF-α in peripheral blood." (PMID 42308351, 2026). "The results showed that there was an increase in TNF-α, IL-1β, and IL-10 production 24h after the infection by M. smegmatis (MOI 1:1) compared to the control group." (PMID 40142455, 2025). "In terms of mRNA expression, the cytokines Interleukin 6 (IL-6), Interleukin 8 (IL-8), Interferon Beta (IFN-β), Interferon Gamma (IFN-γ), and Tumor Necrosis Factor Alpha (TNF-α) were significantly upregulated (P < 0.001) to varying degrees following infection." (PMID 40642060, 2025). "Consistent with the cell infection assay results, K247Q demonstrated the highest levels of proinflammatory cytokines TNF-α, IL-6, and IL-1β, particularly when compared to those produced by K247R at 24 h.p.i." (PMID 40167330, 2025). "Infection-driven hyperinflammatory responses activate multiple immune signaling pathways, including TNF-α and IL-1, which are pivotal in the pathogenesis of IVIG-resistant KD." (PMID 41383607, 2025). "TNF-α is known to promotes recruitment and activation of neutrophils and monocytes to infection sites of infection." (PMID 41472288, 2025). "Biologic agents (like anti-TNF) are a logical consideration in refractory cases, but strict exclusion of infection (especially TB) is mandatory before use." (PMID 41438764, 2025). "TNF-α is one of the earliest and most potent pro-inflammatory cytokines released during an immune response to infection or injury." (PMID 40529359, 2025). "The up-regulation amplitude was IL-6 > IL-1β > TNF-α, and the up-regulation amplitude increased with extended infection time within 18 h." (PMID 40663568, 2025). "Increased body temperature has been shown to amplify proinflammatory responses against infection by increasing the production of cytokines like tumor necrosis factor-α (TNF-α) and interleukin-1 (IL-1α)." (PMID 39806520, 2025). "The control group displayed low expression of inflammatory cytokines, whereas infection significantly upregulated genes such as IL-1β, TNF-α, NF-κB p65, INF-γ, and IL-10 (p < 0.01)." (PMID 41030551, 2025). "At the post-infection time point, TNF-α expression was 0.482 (±0.075)- and 0.325 (±0.019)-fold lower at 1 mM and 10 mM PPA treatment versus MAP, respectively." (PMID 41373953, 2025).